IL27 (interleukin 27)
Diseases named in the same sentence as IL27 in open-access papers (continued):
Sharing a sentence is not in itself a finding about the gene and the disease.
infection (continued). "Overall, our findings suggest that during infection in the absence of IL-27 signaling, a differential expression of CXCR2 and CXCL2 promotes increased migration of mononuclear cells consistent with improved bacterial clearance and tissue homeostasis." (PMID 40977737, 2025). "In control infected pAMs, no changes in the expressions of IL-6, or IL-27 were detected in comparison to non-infected cells both at 6 and 24 h post-infection." (PMID 41155369, 2025). "Infection also resulted in a transient increase in MPs in WT mice, but in the absence of IL-27 this was enhanced at 3 and 5 dpi before returning to baseline at 10 dpi." (PMID 39868131, 2025). "It is known that neonatal mice express elevated levels of IL-27, but a complete description of the cells responsible for its production in the presence and absence of infection is lacking." (PMID 40682363, 2025). "During the later stages of infection, to prevent excessive inflammation and tissue damage, the immune system up-regulated immunosuppressive genes such as CTLA4 and IL27, promoting the differentiation and function of Treg cells and inhibiting excessive Th17 cell response." (PMID 39707535, 2024). "A study reported no changes in circulating levels of IL-27 at several stages of infection, untreated, successfully suppressed viremia with ART." (PMID 38966644, 2024). "In the context of human infections, the role of IL-27 is not well defined and studies of the kinetics of IL-27 expression in vitro and in vivo studies are limited." (PMID 38966644, 2024). "The infection with S. pneumoniae augmented the concentrations of both IFNs (IFN-β and IFN-γ), the inflammatory cytokines IL-6 and IL-12, as well as the immunoregulatory cytokines IL-27 and IL-10 in AMphs cultures." (PMID 39766307, 2024). "In this model, B cell-derived IL-27 is a crucial factor for the survival and function of virus-specific CD4 T cells and TFH cells, enhancing humoral immunity and viral control at the later phase of the infection." (PMID 38966644, 2024). "Additionally, IL-27 signaling promoted survival of virus-specific CD4 T cells and viral control during early infection." (PMID 38966644, 2024). "Although IL-27 can promote T cell responses, mice lacking IL-27Rα or sub-units have stronger T cell responses in various infection models." (PMID 39679172, 2024). "Most reported studies have investigated plasma levels of IL-27 at distinct stages of the infection with no consistent conclusions about the potential in vivo regulation of IL-27 during HIV infection." (PMID 38966644, 2024). "An improved response to infection that is not reliant upon heightened levels of inflammation offers new promise to the potential of antagonizing IL-27 as a host-directed therapy for neonates." (PMID 36891292, 2023). "During infection with the hepatitis B virus, IL-27 was found to be critical for the IFN-I-mediated production of TRIM25; specifically, the knockout of IL27R1 or treatment with the IL-27-neutralizing antibody significantly inhibited TRIM25 expression." (PMID 37391858, 2023). "IL-27, like IFNγ, reduced MCMV production in macrophages 72h post-infection." (PMID 37153622, 2023). "Among the genes that fail to increase during infection in the absence of IL-27 signaling are chemokines, chemokine receptors, and interleukins." (PMID 36891292, 2023). "Infection of MDMs with non-opsonized bacilli induced, at least 10-fold, the synthesis of most tested cytokines except IL-15, IL-27, CCL2 and CCL7." (PMID 37781389, 2023). "Transient blockade of IL‐27 elicits high levels of unique CD127+ and KLRG1+ memory CD4+ T cells, elevates antibody production, and enhances protective immunity against secondary infection." (PMID 37855243, 2023). "After infection, IFN-γ, mainly produced by NK cells and CD4+ T cells, stimulates macrophage activation, inducing high level of Th1 proinflammatory cytokines (e.g., IL-12, IL-2, IL-18, IL-27) and low levels of anti-inflammatory molecules." (PMID 36060742, 2022).
infection (continued). "In our study, IL-27 mRNA levels in the lung were higher at 60 days post infection than at 30 days in both stressed and non-stressed mice." (PMID 36189368, 2022). "The levels of serum ALT, AST, liver IL-6, TNF-α, and IL-1β mRNA and liver pathological injury scores were further increased when pretreated with recombinant IL-27 in WT mice, but these levels were decreased in IL-27r−/− mice after CLP-induced severe infection compared to WT mice." (PMID 33564275, 2021). "Furthermore, recombinant IL-27 treatment in WT mice decreased IL-6 and IL-17 levels, but enhanced production of IL-10 and IFN-γ in the cecal tissue after infection." (PMID 34079555, 2021). "IL-27 plays a role in promoting inflammation in the liver in response to CLP-induced severe infection, but it is not the only cytokine likely to be involved in this process." (PMID 33564275, 2021). "Mincle-/- cells also produced less Nos2, Tnfa, Il27, and Cxcl9 than WT cells upon infection, but the reduction did not meet statistical significance under the tested infection doses and time." (PMID 34320039, 2021). "However, later studies demonstrated that IL-27 also exhibits anti-inflammatory function through inhibition of CD4+ T cell activation, preventing immunopathology during infection with Toxoplasma gondii, Trypanosoma cruzi, and Mycobacterium tuberculosis." (PMID 33593983, 2021). "While there was also no significant increase in the expression of the IL-27 subunit EBI3 during the infection, the gene was well expressed in MDSCs from the control and infected neonates." (PMID 34208904, 2021). "However, the absence of IL-27 data prior to infection limits our understanding of whether septic individuals are predisposed to higher IL-27 levels that constitute a risk factor for infection or if they are elevated as a consequence of infection." (PMID 31818960, 2020). "The cytokine IL-27 that is also considered to be an IL-10 regulator, did not affect IL-10 production during infection." (PMID 32655552, 2020). "• High levels of the P28 subunit of IL-27 are detected in the spleen and liver at weeks 4 and 6 post-infection. • The expression of both IL-27R subunits, including WSX-1 and gp130, are upregulated at week 4 after infection." (PMID 32849534, 2020). "We have previously shown that MDSCs and macrophages are the dominant cellular sources of IL-27 in neonatal mice in the absence of infection." (PMID 31818960, 2020). "DC isolated early after infection of pigs with either of the two CSFV strains showed prominent upregulation of CCL5, CXCL9, CXCL10, CXCL11, and XCL1, as well as of the cytokines TNFSF13B, IL6, IL7, IL12B, IL15, IL27." (PMID 32733474, 2020). "On the other hand, IL-27 can enhance NK cell antitumor activity, including upregulation of Tbet and granzyme B in vivo, both of which we found to require IL-27 for optimal upregulation after LCMV Cl13 infection." (PMID 29593047, 2018). "Together, these data show that IL-27 is produced by multiple DC subsets (i.e. pDCs, CD11b+ and CD8+ cDCs) after MCMV infection and that DC-derived IL-27 is required to restrict a cytotoxic phenotype in antiviral CD4 T cells upon infection." (PMID 30044874, 2018). "Similarly, to live infection, both subtypes of IAV HA significantly attenuated HKSP induced IL-12p70 (n = 3), with a significant down-regulation of pneumococcus induced IL-27 (n = 6) by H1N1 HA." (PMID 30192848, 2018). "The median value of IL-27 was significantly higher in episodes with infection at 1.5 (0.9–2.9) ng/mL versus 1.1 (0.7–1.8) ng/mL (p-value < .001) in episodes without infection." (PMID 30475852, 2018). "In the context of infection with T. cruzi, it was not clear what sensing pathways were strictly involved in the IL-27 production." (PMID 29033934, 2017). "Although both C57BL/6 and BALB/c strains are considered susceptible models for experimental VL, here we showed that only BALB/c and not C57BL/6 mice increased IL-27 in the serum early after i.p. infection with L. infantum." (PMID 27867384, 2016).
infection (continued). "To examine whether early IFN-induced IL-27 production shaped antiviral responses, we treated MCMV-infected mice with neutralizing anti-IL-27 antibody at the time of infection." (PMID 27926930, 2016). "While IL-27 remained unchanged in the serum of infected C57BL/6 mice, infected BALB/c showed an early increase that was significant 4 days after infection (p ≤ 0.05) and always higher than the IL-27 levels of C57BL/6 mice (p ≤ 0.05 comparing the day 2 and p ≤ 0.01 the day 4 after infection)." (PMID 27867384, 2016). "The difference observed in the IL-27 production between the two mice strains in this study was confirmed at the cellular level, as splenic DCs from BALB/c but not from C57BL/6 mice upregulated the expression of IL-27p28 after infection." (PMID 27867384, 2016). "Similarly, at day 7 post-infection, HepaRG cells infected with HBV showed modest reductions in HBsAg levels after treatment with IL-27." (PMID 28058287, 2016). "In the children infection groups, the amounts of IL-27 and IL-33 as produced by their PBMC increased in order G0 < G1 < G3+; the IL-27 production remained unchanged post anti-parasite treatment (pT), whilst the cellular IL-33 production returned pT to the lowest levels as found in G0 children." (PMID 25698903, 2015). "Furthermore, infection of WT and Ifnar1−/− macrophages revealed that type I IFN signaling was required for IL-27 production upon M. tuberculosis infection (Fig. 1Gii)." (PMID 25187652, 2014). "IL-27 does not appear to regulate the initial priming or differentiation of Th1 cells during infection, unless IL-4 is present, when IL-27 is required to limit Th2 differentiation and enable Th1 responses to develop." (PMID 23593003, 2013). "On the contrary, WSX-1−/− mice generate more IFNγ-producing CD4+ T cells than wild-type mice after infection with Toxoplasma gondii, indicating that IL-27 signal is not necessary for the generation of Th1 immunity to the infection." (PMID 24068935, 2013). "IL-27 is an important and non-redundant regulator of effector T cell accumulation in non-lymphoid tissues during infection." (PMID 24244314, 2013). "When mice were monitored for survival it was found that deaths occurred in all control groups beginning at day 8 post-infection, but not in the IL-27-expressing group, suggesting a direct role for IL-27 in mediating resistance." (PMID 22479310, 2012). "We next conducted CART analysis to determine whether a combination of serum IL-27 and PCT concentrations could further improve the ability to predict infection in critically ill patients." (PMID 23107287, 2012). "It is interesting that post infection, perhaps upon viral pathogenesis we no longer see and increase in IL-27 gene expression." (PMID 21701683, 2011). "In particular, the neutralization of IL-27 by soluble receptor has been shown to augment the levels of TNF-α and IFN-γ during early infection and may allow macrophages to better combat Mtb at a critical time." (PMID 21197399, 2011). "(D) Schematic of infection of WT and Il27–/– mice for E and F. (E) Numbers of LTHSCs and granulocyte progenitors (GPs) (CD3−, NK1.1−, B220−, CD117+, CD34+, CD16/32hi, Ly6C+, CD135−, CD115−) in the bone marrow of WT and Il27–/– infected mice throughout infection." (PMID 41396163, 2025). "It was reported that the stimulation of macrophages with LPS or the infection with Gram-negative pathogens not only induces changes in their expression and production of inflammatory factors but in addition, modulate regulatory factors like IL-10 and IL-27." (PMID 40141330, 2025). "IL-27 had a better performance in distinguishing neonates with true infection from neonates without infection, and a combined performance of IL-27 with PCT in the UCB and at 24 h of life showed greater prediction of EONS with p < 0.01 for each parameter/parameter combination." (PMID 40171168, 2025).
infection (continued). "The studies presented here show that infection with T. gondii results in increased activity of HPSC and downstream progenitors associated with emergency myelopoiesis; however, in the absence of IL-27, HSPCs display a skewed developmental program that resulted in enhanced monopoiesis." (PMID 39868131, 2025). "In the absence of IL-27, a lethal, overactive immune response develops during infection." (PMID 38376210, 2024). "Further studies are needed to elucidate whether IL-27 exhibits similar divergent roles in other HIV-1 target cells, such as macrophages and dendritic cells, and if so, to search for the contribution of BST-2/Tetherin in those infection settings." (PMID 36602368, 2023). "Therefore, IL‐27‐sensitive fate decision of PbT‐II cell differentiation occurs early after Pcc infection and that, once the decision is made, active infection is not required for their maintenance." (PMID 37855243, 2023). "Thus, our data suggest that while IL-27 is present in the lungs at 60 days of infections, differences in IL-27 production are not responsible for differences in CD4 T cell and IL-10 expression between young and old stressed mice." (PMID 36189368, 2022). "However, later studies confirmed that IL-27Rα−/− mice developed normal Th1 response after infection, and IL-27 could induce IL-10 and SOCS3 to suppress Th1 cells, suggesting the bidirectional role of IL-27 in Th1 cells." (PMID 34299138, 2021). "However, the relationship between IL-27 and liver macrophages in liver injury after severe infection is not yet clear." (PMID 33564275, 2021). "Furthermore, the addition of IFNγ resulted in improved control of parasite growth in both Il27ra-/- and WT macrophages, while the addition of IL-27 had no significant impact on the establishment of infection or growth of parasites in WT macrophages." (PMID 33049000, 2020). "Hence, inhibition of the first and middle steps of glycolysis results in reduced cytokine production by bona fide Th1 cells during infection and had no impact on Tr1 cells, suggesting that IL-27 signalling regulates glycolysis specifically in Th1 cells." (PMID 33049000, 2020). "Thus, TLR4, IL27, and TNF were activated across all groups; IFNG was exclusively activated by AMTB-127 and AMTB-205; PTGS2 was activated in AMCTs and AMTBs in response to infection with Mtb UT205, whereas TLR2 was only activated in response to Mtb UT127." (PMID 32373118, 2020). "Interestingly, we found a significant increase in IL-27 serum concentrations in wt but not in C5ar1−/− mice after infection." (PMID 32733463, 2020). "Together, these data show that during MCMV infection, the development of a cytotoxic phenotype in CD4 T cells correlates with expression of the transcription factor T-bet and not Eomes, and accordingly IL-27 negatively regulates T-bet expression in CD4 T cells upon infection." (PMID 30044874, 2018). "Higher levels of internalization of exponential phase S. typhimurium were detected at 1 hour post-infection compared to stationary phase at 1.5 hours post-infection; however, IL-27 did not impact the internalization of either exponential or stationary phase S. typhimurium." (PMID 30209294, 2018). "Depletion of IL-6 in the early stages of infection resulted in enhanced disease characterized by an influx of IFN-γ secreting virus specific T cells into the lungs and airways, dysregulation of regulatory T cell responses and reduced production of the immune-regulatory cytokines IL-10 and IL-27." (PMID 28953978, 2017). "Importantly IL-27 was readily detected in the airways of RSV infected, but not uninfected, mice as early as 12 hours post infection, with peak of IL-27 seen in the airways and lungs of infected mice between day 4 and 7 p.i.." (PMID 28953978, 2017). "Importantly here we found that IL-6 mediated immune-regulation occurs via the induction of IL-27 in the airways after infection, without any effect on peak viral loads or viral clearance." (PMID 28953978, 2017).
infection (continued). "Moreover, malaria infection induced IFN-γ production, which augmented IL-27 expression, and the IL-27 then promoted the expansion and mobilization of LSK cells into the spleen, resulting in enhanced myelopoiesis to resolve the infection." (PMID 26991425, 2016). "Thus, IL-27 production in response to MCMV is dependent upon type-1 IFNR signaling, and this axis acts during the initial days of infection to promote the accumulation of MCMV-specific IL-10+CD4+ T cells, subsequently promoting virus persistence and shedding from the mucosa." (PMID 27926930, 2016). "The blood stage of malaria infection was revealed to enhance IL-27 expression through interferon-γ production, and IL-27 then promoted the expansion of LSK cells, differentiating and mobilizing them into the spleen, resulting in enhanced production of neutrophils to control the infection." (PMID 26991425, 2016). "We can also suggest that the IL-27 produced in response to infection shall not be a product of inflammation as BALB/c mice present higher parasite loads than C57BL/6 during the first days of infection, a difference that is counteracted by the treatments." (PMID 27867384, 2016). "We revealed that an axis involving type-I IFN and IL-27 promotes the generation of peripheral IL-10-producing T cells that suppress antiviral immunity, suggesting that CMV exploits this immune-regulatory pathway induced early in infection to ensure viral persistence within mucosal tissue." (PMID 27926930, 2016). "However, our data does not preclude an IL-10-independent inhibitory function for IL-27 during the later stages of infection." (PMID 27926930, 2016). "Neither IL-27 nor ICOS played a role in the development of parasite-specific CD4+ YFP+ T cell responses during infection, implying that these pathways specifically modify the induction of IL-10 expression, rather than modifying the initial development of the Th1 response." (PMID 26459508, 2016). "Thus, our data identify IL-27 signaling as a novel pathway to prevent early mortality via inhibiting hyperactivation of CD4+ Th1 cells and their excessive secretion of IFN-γ during infection with African trypanosomes." (PMID 26222157, 2015). "Moreover, this treatment increased the production of IL-12, IL-23, IL-27, IL-15, and IL1β such that negative correlations between the levels of these cytokines with both the infection ratio and number of intracellular parasites were observed." (PMID 26488744, 2015). "By contrast, the pathways by which IL-27 inhibits effector T cell accumulation in non-lymphoid tissues during infection are poorly understood, but may include limiting CD4+ T cell proliferation or enhancing cellular apoptosis in situ." (PMID 24244314, 2013). "IL-27 limits IFN- γ production by CD4+ T cells during various infections, attenuates the development, but not necessarily maintenance, of Th17 responses by limiting retinoid-related orphan receptor (ROR)c expression and stimulates IL-10 production by multiple effector CD4+ T cell populations." (PMID 23593003, 2013). "Finally, the level of DC-SIGN, a C-type lectin important in promoting HIV-1 trans infection between DCs and T cells, was not differentially expressed between iDCs treated with or without IL-27." (PMID 23527130, 2013). "As the infection of a pseudo type HIV-1 virus, which could only result in a single round of infection, was also inhibited by IL-27 treatment and the proviral copy number was decreased in the treatment arm, this suggested that IL-27 works by suppressing HIV-1 at a certain step in the HIV life cycle." (PMID 23527130, 2013). "It is also possible that other cytokines may be involved in the regulation of IL-27 function; interestingly, previous studies have reported high levels of IFN in HIV-infected patients with advanced infection, and, furthermore, it has been reported that IL-27 can induce IFN expression." (PMID 23049843, 2012).